EZH2 (enhancer of zeste 2 polycomb repressive complex 2 subunit)
Diseases named in the same sentence as EZH2 in open-access papers (continued):
Sharing a sentence is not in itself a finding about the gene and the disease.
hepatocellular carcinoma (continued). "A study has revealed that HBx not only inhibits the mRNA expression level of AIM2 by stabilizing the enhancer of zeste homolog 2 (EZH2), but also promotes AIM2 protein degradation in a proteasome-dependent manner in HBV-infected hepatocellular carcinoma (HCC) cells." (PMID 36298831, 2022). "There is a negative feedback loop in which EZH2 can reduce miRNA expression in hepatocellular carcinoma to mediate immune evasion." (PMID 35236381, 2022). "Previous evidence showed that lncRNA UCA1 was up-regulated in hepatocellular carcinoma, and EZH2 showed a negative correlation with lncRNA UCA1 level." (PMID 34868904, 2021). "To date, except for MCL1 which has been proven by us and other literature studying hepatocellular carcinoma, among the validated miR-26a targets, HMGA1, PTEN, EZH2, MITF, DNMT3B, TGF-beta, and Ezh2 have been demonstrated to regulate chemoresistance." (PMID 33816494, 2021). "In hepatocellular carcinoma, PVT1 promoted cell proliferation by recruiting Ezh2." (PMID 34335862, 2021). "The expression levels of SMG5, EZH2, ZNF239, and IGF2BP3 in different hepatocellular carcinomas were higher than those in the normal group in the Roessler Liver (34868_ at), Roessler Liver (203358_s_at), Roessler Liver (206261_at), and Roessler Liver (203819_s_at) studies." (PMID 33297932, 2020). "Clinical samples from HCC patients with immune-activated microenvironments showed negative correlations between EZH2 and PD-L1 expression in hepatoma cells." (PMID 31727135, 2019). "Similarly, in the hepatocellular carcinoma cell line HEPG2, another miRNA, miR-137, targeted EZH2 mRNA that led to decreased cell migration and invasion." (PMID 34991274, 2018). "Similarly, in hepatocellular carcinoma (HCC), hypoxia and HIF-1α increases NIPP and EZH2 levels, an effect that then results in augmented invasive and metastatic potential." (PMID 30510924, 2018). "Meanwhile, EZH2, another Polycomb-group (PcG) protein associated with histone modification of H3K27me3, showed no change in abundance, consistent with a study reporting that USP22 silencing did not change EZH2 in hepatocellular carcinoma." (PMID 28415621, 2017). "Other studies have identified a double-negative feedback loop between EZH2 and miR-26a in hepatocellular cancer, since miR-26a, which directly targets EZH2 at a post-transcriptional level, is also abrogated by EZH2 overexpression." (PMID 27793053, 2016). "Coregulation of genes by HULC and EZH2 or HULC and MLL1 was limited; however, there was significant negative correlation between HULC-regulated genes in SK-Hep-1 cells with genes regulated in hepatocellular carcinomas." (PMID 26317792, 2015). "Furthermore, in hepatocellular carcinoma, BMAL1 was shown to transcriptionally inhibit glycerol-3-phosphate acyltransferase mitochondrial (GPAM) expression in an Enhancer of zeste homolog 2 (EZH2)-dependent manner, suppressing tumor cell growth by interfering with glycolipid metabolic processes." (PMID 41228459, 2025). "Pharmacological or genetic inhibition of EZH2 led to an increase in the expression of NKG2D ligands and enhanced eradication of hepatocellular carcinoma (HCC) cell." (PMID 39161385, 2024). "Moreover, EZH2 was identified as a target of miR-124, and a notable negative correlation between EZH2 mRNA levels and miR-124 was observed in hepatocellular carcinoma (HCC) tissues." (PMID 38534385, 2024). "For instance, EZH2 and EED are direct targets of the tumor suppressor miR-101 in hepatocellular carcinoma (HCC) cells." (PMID 37345170, 2023). "MRPL54, EZH2, PPARGC1A, and EIF2AK4 were identified as hub genes in bioinformatics analysis of hepatocellular carcinoma (HCC)." (PMID 35719986, 2022). "Despite preclinical studies in hepatocellular carcinoma, PCa, head and neck cancer and Ewing sarcoma showing that the combination of EZH2 inhibitors and CPIs has a synergistic effect, there are no studies investigating the immunological consequences of these combinations." (PMID 36135315, 2022).
hepatocellular carcinoma (continued). "Moreover, activation of IFNγ-STAT1 signaling is not influenced by EZH2 expression in hepatoma cells." (PMID 31727135, 2019). "Here, we investigated the ability of the epigenetic modifier, enhancer of zeste 2 polycomb repressive complex 2 subunit (EZH2), to regulate the expression of immune checkpoint inhibitor, programmed death-1 ligand 1 (PD-L1) in hepatocellular carcinoma (HCC)." (PMID 31727135, 2019). "Thus, this study concluded that EZH2 is a sensitive and reliable immune marker of hepatocellular carcinoma, compared to non-malignant hepatocellular lesions." (PMID 23111165, 2012). "For example, circLRIG3 preferentially located in the nucleus and interacts with both EZH2 and STAT3 in hepatocellular carcinoma to form a circRNA-protein complex, facilitating EZH2-induced activation of STAT3 signaling and promoted HCC cell proliferation and metastasis." (PMID 35986300, 2022). "Moreover, in hepatocellular carcinoma and PCa, a negative correlation between EZH2 and PD-L1 was reported, which may result from the upregulation of H3K27me3 levels in the promoters of CD274 and IRF1." (PMID 36135315, 2022). "EZH2 could be recruited to the target gene/miRNA promoters via the DNA-binding protein YY1 and mediate histone H3 lysine 27 trimethylation to silence the expression of genes/miRNAs involved in skeletal muscle differentiation and hepatocellular carcinoma progression." (PMID 32635336, 2020). "EZH2, a histone methyltransferase, has been shown to involve in cancer development and progression via epigenetic regulation of tumor suppressor microRNAs, whereas BMI1, a driver of hepatocellular carcinoma (HCC), is a downstream target of these microRNAs." (PMID 33168810, 2020). "However, neither IL-6 nor TNFα could induce PD-L1 expression on hepatoma cells, with or without EZH2-silencing." (PMID 31727135, 2019). "Downregulation of canonical Wnt pathway by PCI has been described in a model of hepatocellular cancer, in which HDAC8 physically interacts with chromatin modifier EZH2 to repress Wnt antagonists, activating Wnt pathway." (PMID 33015043, 2020). "It has been reported that CAFs promote hepatocellular carcinoma angiogenesis and metastasis through VEGF-induced upregulation of EZH2 and subsequent downregulation of vasohibin 1, a negative regulator of angiogenesis, emphasizing an important role of EZH2 in mediating the function of CAFs." (PMID 36038549, 2022). "In hepatocellular carcinoma, PRC2 complex epigenetically repressed miR-101 in a c-Myc-mediated manner, which in turn inhibited the expression of two subunits of PRC2 (EZH2 and EED), thus creating a double-negative feedback loop that regulates the process of carcinogenesis." (PMID 27385092, 2016).
ovarian carcinoma (235 papers, 2011 to 2026). A malignant neoplasm originating from the surface ovarian epithelium. "Significant reduction in EZH2 mRNA levels was observed in ovarian cancer stem cells transfected with miRNA-98, which was associated with cell cycle arrest and reduced proliferation rates." (PMID 40042761, 2025). "For instance, lncRNA plasmacytoma variant translocation I (PVT1) interacts with EZH2 to down-regulate miRNA-214 expression, leading to an increase in proliferation and metastasis of ovarian cancer cells." (PMID 35236381, 2022). "Enhancing miRNA-101 expression is associated with EZH2 down-regulation and a subsequent decrease in proliferation and migration of ovarian cancer cells." (PMID 35236381, 2022). "Knockdown of EZH2 in an epithelial ovarian cancer cell line caused an increase in TIMP2 levels along with decreased levels of the active form of the matrix metalloproteases, MMP2 and MMP9." (PMID 36359771, 2022). "ARID1A represents a particularly interesting amiR-4 target since its deletion/mutation sensitises ovarian cancer cells to EZH2 methyltransferase inhibition with the small molecule GSK126 in a synthetic lethal fashion." (PMID 35393414, 2022). "For instance, moderate and high expression levels of EZH2 are associated with unfavorable prognosis of patients with ovarian cancer." (PMID 35236381, 2022). "Among epithelial ovarian cancers, 66% have elevated EZH2 expression in both the tumor cells and the associated epithelium." (PMID 36359771, 2022). "Despite interest in the association between EZH2 function, ovarian CSCs, and ovarian cancer, the molecular mechanisms underlying the tumorigenic function of EZH2 in ovarian cancer and the relationship with CHK1 signaling have not yet been considered." (PMID 33408782, 2021). "EZH2 has emerged as a highly attractive target based on its elevated expression in ovarian cancer and its association with tumor chemoresistance and poor clinical outcomes." (PMID 33408782, 2021). "Later studies demonstrated that EZH2 is upregulated in ovarian cancer and that this upregulation is associated with a high proliferation index, a high tumor grade, and poor prognosis." (PMID 33163485, 2020). "Mutation in the SWI-SNF subunit ARIDIA causes synthetic lethality during the inhibition of EZH2 in ovarian cancer xenograft." (PMID 33003334, 2020). "By analyzing samples from the TCGA database, we found that hsa-mir-101-1, hsa-mir-26a-2, and hsa-let-7e were negatively associated with EZH2 expression in ovarian cancer." (PMID 33718109, 2020). "Higher expression of EZH2 or H3K27m3e was associated with cisplatin resistance in ovarian cancer, non-small cell lung cancer, osteosarcoma, and glioblastoma." (PMID 31181810, 2019). "A targeted therapy for ARID1A-deficient tumors was developed based on data demonstrating the synthetic lethality of EZH2 inhibition in ARID1A-mutated ovarian cancer cells." (PMID 31043675, 2019). "Here, the authors demonstrate that the switch of the SWI/SNF catalytic subunits from SMARCA4 to SMARCA2 drives resistance to EZH2 inhibitors in ARID1A-mutated ovarian cancer cells." (PMID 30297712, 2018). "The high expression of EZH2 has been implicated in maintenance of the cisplatin-resistant subpopulation of cells in ovarian carcinoma and contributes to acquired-tolerance for platinum-based chemotherapy." (PMID 30064416, 2018). "Here we show that the switch of the SWI/SNF catalytic subunits from SMARCA4 to SMARCA2 drives resistance to EZH2 inhibitors in ARID1A-mutated ovarian cancer cells." (PMID 30297712, 2018). "Here, we showed that EZH2 is up-regulated in ovarian cancer and is associated with tumor metastasis and poor survival by mRNA sequencing and microarray results from databases." (PMID 28620234, 2017).
ovarian carcinoma (continued). "After confirming that TIMP2 is repressed by EZH2 in ovarian cancer, we subsequently investigated the underlying mechanism." (PMID 28620234, 2017). "This prediction is also consistent with the previous findings that high expression of EZH2 is associated with poor survival in ovarian cancer patients." (PMID 25545504, 2014). "A recent study showed that EZH2 is a key regulator of tumor angiogenesis through its expression in cancer associated endothelial cells in human ovarian cancer." (PMID 24294976, 2013). "EZH2 is often over-expressed in epithelial ovarian cancer (EOC) cells and in ovarian cancer-associated stromal endothelial cells." (PMID 23494175, 2013). "Ezh2 silencing in the tumor-associated endothelial cells using chitosan-packaged siRNA significantly inhibits tumor growth in an orthotopic ovarian cancer model." (PMID 23109879, 2012). "Expression profiling indicated that EZH2 transcripts are up-regulated in ovarian carcinoma-associated endothelial cells, and modulated EZH2 expression was described to affect genes associated with endothelial differentiation." (PMID 21297974, 2011). "For example, our predictions suggested a potential relationship between let-7b and EZH2, which aligns with a previous study demonstrating that the loss of let-7b leads to the upregulation of EZH2 expression, consequently promoting ovarian cancer growth both in vitro and in vivo." (PMID 39871129, 2025). "Moreover, EZH2 inhibitor GSK126 can lead to the decline of ovarian cancer carrying ARID1A mutation in vivo." (PMID 38008753, 2023). "Additionally, in ovarian carcinoma, reduced EZH2 phosphorylation caused by CDK2 inhibition was found to activate downstream ESR1." (PMID 35846880, 2022). "EZH2 overexpression also causes loss of cell cycle control in epithelial ovarian cancers." (PMID 36359771, 2022). "Using the same ovarian cancer model, Zou and colleagues showed that Ezh2 deficiency in T cells suppressed control of tumor progression, while combined Ezh2 and DNMT inhibitors improved the efficacy of anti-PD-1 therapy by increasing the production of CXCL9 and CXCL10." (PMID 33403469, 2021). "Accumulating evidence has demonstrated the important role of high EZH2 expression in the malignant progression of epithelial ovarian cancer, but the underlying regulatory mechanism remains largely unknown and warrants further investigation." (PMID 33718109, 2020). "Since chemotherapy response was an independent factor influencing prognosis, we next evaluate whether EZH2 associated pathways representing varied chemotherapy response status were of prognostic significance to survival of ovarian cancer patients." (PMID 32435534, 2020). "In addition to the well-known general involvement of EZH2 in cell cycle regulation, which especially affects cells with high mitotic activity, it was also found that a loss of EZH2 in ovarian cancer stem cells is correlated with growth inhibition." (PMID 31317325, 2019). "Thus pharmacological inhibition of EZH2 represents a novel treatment strategy for ovarian cancers involving ARID1A mutations." (PMID 30064416, 2018). "EZH2 has been associated with epithelial to mesenchymal transition in ovarian cancers." (PMID 29575713, 2018). "Similarly, targeting EZH2 in Arid1a-mutated ovarian cancer cells shows synergistic sensitivity." (PMID 39123453, 2024). "However, the mechanism underlying EZH2 promotion of ovarian cancer metastasis remains elusive." (PMID 28620234, 2017). "Notably, EZH2 expression is upregulated in ovarian cancer stem cell-like cells enriched by chemotherapy and knockdown of EZH2 leads to loss of stem cell-like properties in these cells, such as anchorage-independent growth and tumor growth in xenograft mouse model." (PMID 23494175, 2013). "In this study, we systematically investigate the correlation between Tazemetostat, a highly selective EZH2 inhibitor, and alterations in the eccDNA landscape and transcriptional programs in ovarian cancer." (PMID 41744650, 2026).
ovarian carcinoma (continued). "Karakashev's research group found that EZH2 inhibitors are effective in treating epithelial ovarian cancer with high expression of CARM1." (PMID 39964832, 2025). "As recently demonstrated, USP7 specifically targets EZH2 in prostate and ovarian cancers, thus affecting EZH2-mediated angiogenesis." (PMID 41157055, 2025). "Loss of EZH-2 antagonists such as ARID1A and SMARCA2/4 leads to the repression of tumor suppressor genes in ovarian cancer." (PMID 41301911, 2025). "Surprisingly, higher expressions of DNMT3B and EZH2 are reported in ovarian cancer and, as per RNA-seq results, CHD4 expression is positively correlated with EZH2 in ovarian cancer patients." (PMID 40004553, 2025). "The role of EZH2 in modulating the TIME extends to ovarian cancer, where its inhibition synergizes with other epigenetic therapies to reshape immune landscapes." (PMID 41029427, 2025). "In ovarian cancer models, EZH2-mediated histone methylation and DNA methyltransferase programmed death-ligand 1(PD-L1)-mediated DNA methylation inhibit chemokine CXCL9 and CXCL10 expression, promoting tumor aggressiveness." (PMID 40042761, 2025). "They introduced a novel strategy for treating ovarian cancer by targeting CARM1 with enhancer of zeste homologue 2 (EZH2) and ADP‐ribose polymerase (PARP) inhibitors." (PMID 39964832, 2025). "The following discusses the crosstalk between ceRNAs with KDM5 family members and EZH2 in ovarian cancer development." (PMID 39967908, 2025). "Increased EZH-2 activity can be found in up to 85% of epithelial ovarian cancer cases, yet its biological impact is influenced by the interplay of EZH-2 and other epigenetic regulators such as the components of the BAF complex." (PMID 41301911, 2025). "Studies have found that EZH2 is highly expressed in ovarian cancer and enhances tumor invasiveness by inhibiting the MAF gene." (PMID 40732683, 2025). "Similar action was also found in ovarian cancer stem cells that EZH2 transcriptionally up-regulates checkpoint kinase 1 expression by directly binding to its promoter, therefore promoting ovarian cancer chemoresistance." (PMID 40028035, 2025). "Histone Modifications and Chromatin Remodeling in Ovarian Cancer: Histone methylation (such as EZH2-mediated H3K27me3) and deacetylation (HDAC-mediated) affect gene expression by regulating chromatin structure." (PMID 40732683, 2025). "This phenomenon seems to be the pathophysiologic base of this rare form of ovarian cancer, as EZH-2 inhibition seems to have therapeutic potential." (PMID 41301911, 2025). "EZH2 was found to be important in promoting resistance to chemotherapy in ovarian cancer cells, as well as their ability to actively proliferate." (PMID 38669256, 2024). "The specific H3K27 methyltransferase enhancer of zeste homolog 2 (EZH2) confers chemoresistance on ovarian cancer cells through H3K27 methylation." (PMID 38539161, 2024). "For instance, the set with the second greatest significance was LU_EZH2_TARGETS_UP (P < 0.001; false discovery rate [FDR], q < 10–3), which includes genes that were upregulated in SKOV3ip1 ovarian cancer cells upon knockdown of EZH2." (PMID 38886296, 2024). "Recent research has highlighted that, similar to many other cancers, ovarian cancer is marked by alterations in a range of epigenetic regulators, including EZH2, SMARCA2/4, and ARID1A." (PMID 39605897, 2024). "LncRNA PVT1 is highly expressed in epithelial ovarian cancer tissues, inhibits the expression of miR‐214 by binding EZH2 and promotes the progression of ovarian cancer." (PMID 38098223, 2024). "For example, CAFs in ovarian cancer induce high expression of EZH2 in cancer cells, leading to increased cancer cell migration." (PMID 38988323, 2024). "Against this backdrop, our investigation delves into the intricate mechanisms governing CENP-O’s activity in ovarian cancer cells, shedding light on its downstream effects on gene expression, notably implicating EZH2 and JUN signaling pathways." (PMID 38890751, 2024).